CDCP1 (CUB domain containing protein 1)
Diseases named in the same sentence as CDCP1 in open-access papers (continued):
Sharing a sentence is not in itself a finding about the gene and the disease.
cancer (109 papers, 2011 to 2026). A tumor composed of atypical neoplastic, often pleomorphic cells that invade other tissues. "Elevated expression of CDCP1 has been linked to poor prognosis and enhanced invasiveness in several preclinical cancer models." (PMID 41488282, 2026). "Elevated CDCP1 expression is frequently associated with poor prognosis, including tumor growth, metastasis, recurrence, and reduced overall survival in many cancers." (PMID 40892739, 2025). "Dysregulation of CDCP1 expression has been associated with multiple cancers, including leukemia, metastatic colon cancer, and breast cancer." (PMID 39441449, 2024). "Proteins including CXCL14, GDF15, HAVCR1, and CDCP1 were identified as predominant contributors to the risk of cancer." (PMID 38016990, 2023). "Researchers recently identified a transmembrane protein, CUB-containing domain protein 1 (CDCP1), as a promising therapeutic target and diagnostic biomarker for malignant tumors." (PMID 36362412, 2022). "This is the first study to reveal the association of CDCP1 with acquired resistance to osimertinib in cancer cells." (PMID 35643725, 2022). "CDCP1 is a transmembrane scaffold of Src tyrosine kinase, and its upregulation has been implicated in tumor progression, particularly cancer invasion and metastasis." (PMID 35085554, 2022). "CDCP1 is a transmembrane glycoprotein chemotactic for T-cells that has been associated with cell adhesion and cancer development." (PMID 34863228, 2021). "CUB-domain containing protein 1 (CDCP1) is a cancer associated cell surface protein that amplifies pro-tumorigenic signalling by other receptors including EGFR and HER2." (PMID 32104500, 2020). "Thirdly, CDCP1 expression is associated with cancer stages and progression, which is considered to be barely lost in the process of tumor progression." (PMID 32308755, 2020). "CDCP1 is a transmembrame glycoprotein that is highly overexpressed in multiple cancer types and overexpression of CDCP1 is associated with poor prognosis in cancer patients." (PMID 30796352, 2019). "CDCP1 has been previously implicated as an elevated marker in solid cancers and a driver of cancer cell growth, metastasis, and tumor progression." (PMID 29359686, 2018). "The prognostic value of CDCP1 has been reported in human cancers, wherein CDCP1 overexpression is associated with a poor prognosis in certain epithelial tumors, but our study is the first description of its clinical significance in TNBC patients." (PMID 27626701, 2016). "Cell motility is important for cancer cell metastasis and CDCP1 has been implicated in the motility of other cancer cell lines." (PMID 25301083, 2014). "There is immuno-histochemical evidence showing reduced Trask/CDCP1 expression in some cancers and biochemical data showing that a reduction or loss of expression in some cancer cells due to promoter hypermethylation." (PMID 21559459, 2011). "We hypothesized that CDCP1 expression is associated with hallmark cancer signaling pathways and transcriptionally inferred TME remodeling in PDAC." (PMID 41488282, 2026). "We first tested whether pharmacologic inhibition of the SMYD3/CDCP1 signaling axis in cancer cells blunts paracrine activation of cancer-associated fibroblasts (CAFs)." (PMID 41301830, 2025). "CDCP1 is a known protein implicated in malignancies of multiple cancers." (PMID 36978083, 2023). "In addition, we collected ascites and serum samples from women with EOC and non-cancer and determined the expression level of CDCP1 by enzyme-linked immunosorbent assay (ELISA)." (PMID 37469398, 2023). "Further, targeting a specific cell-surface antigen could result in immunoediting and loss of expression of CDCP1 in cancer cells, potentially leading to tumor relapse over time." (PMID 35166242, 2022). "Moreover, CDCP1 up-regulation is associated with the worse overall survival and recurrence-free survival of cancers." (PMID 31417870, 2019).
cancer (continued). "ADAM9 and CDCP1 are oncogenic membrane proteins that have been linked to cancer metastasis." (PMID 28537886, 2017). "However, the only gene product in this network that has been explicitly implicated in the movement of cancer cells expressing specifically oncogenic KRas mutants is CDCP1." (PMID 27894102, 2016). "The aim of this study was to systematically evaluate the association of CDCP1 expression with TME composition, mutational landscape, and hallmark cancer signaling pathways, and patient survival in PDAC using large-scale transcriptomic datasets." (PMID 41488282, 2026). "CUB domain-containing protein 1 (CDCP1) has emerged as a molecule of growing interest in cancer biology, owing to its role in promoting cell adhesion, motility, and survival across multiple epithelial malignancies." (PMID 41488282, 2026). "ROCK1, located in 18q11.1, is a member of the serine/threonine kinases family, and CDCP1 was previously suggested to possibly play a role in promoting cancer metastasis." (PMID 40556338, 2025). "We further demonstrated that PDAC patients with the elevated proportion of CDCP1+FTL+ CAFs in TME suffered from advanced cancer stage, distant metastasis, and poor outcomes." (PMID 40019403, 2025). "Although CDCP1 and ACL8 expression is also reduced in SKBR3-L cells, their low expression has been associated with favourable outcomes in cancers." (PMID 40946111, 2025). "SMYD3-driven CDCP1 expression in cancer cells indirectly reprograms neighboring fibroblasts toward a myofibroblastic, pro-tumor phenotype, bridging nuclear epigenetic control with stromal activation." (PMID 41301830, 2025). "The widespread upregulation renders CDCP1 a significant clinical potential in cancers, serving as both a biomarker and a therapeutic target." (PMID 40892739, 2025). "Overexpression of CDCP1 in various cancers, including cancer of the colon, lung, breast, renal, and pancreas, is highly correlated with cancer progression; thus, it is expected to serve as a new biomarker for diagnosis." (PMID 40892739, 2025). "Background/Objectives: CD318 (also known as CDCP1) is a transmembrane protein that is overexpressed in many cancers and contributes to tumor progression, invasion, and metastasis by activating SRC family kinases through phosphorylation." (PMID 40725832, 2025). "As described, CDCP1 plays essential roles in promoting cancer cell survival, growth, metastasis, and resistance to chemotherapy and targeted agents." (PMID 40892739, 2025). "Further analysis showed that t-PA activity was highly correlated with CDCP1 cleavage in these cancer cells; thus, t-PA is responsible for CDCP1 activation." (PMID 39441449, 2024). "We validate the generality of EDS and apply it to effectively block the proteolysis of cell surface receptors in cancer (CDCP1 and EphA2) and the proteolytic activation of three proenzymes in cell migration (MMP1, MMP3, and MMP9)." (PMID 38683990, 2024). "Stimulation of CDCP1 expression promotes CDCP1-mediated cancer cell migration in vitro and exacerbates the pro-carcinogenic effects, possibly by promoting the formation of a tumor inflammatory microenvironment." (PMID 39497803, 2024). "The CUB domain-containing protein 1 (CDCP1) is a type I transmembrane glycoprotein that is widely upregulated in the pathogenesis of various malignant tumors, including those of the liver and pancreas." (PMID 39497803, 2024). "CD318 or Cub domain-containing protein 1 (CDCP1) is a cell-surface glycoprotein expressed by fibroblasts and the epithelium of normal and cancer cells." (PMID 39840036, 2024). "Immunohistochemical results showed various staining intensities, ranging from weak to intense, of ADAM9, CDCP1, and t-PA expressions in the cytoplasm or at the cell membrane of most cancer cells within the cancer cell nests of OSCC specimens." (PMID 39441449, 2024). "CUB domain containing protein 1 (CDCP1) is a type I transmembrane glycoprotein highly expressed in various cancers." (PMID 36862682, 2023).
cancer (continued). "Numerous reports show that upregulated CDCP1 is commonly found in cancer patients, many of whom show poor overall survival probability." (PMID 37013960, 2023). "CDCP1 has been reported to regulate metastasis through c-Src-kinase and PKCδ signaling in various cancers." (PMID 36862682, 2023). "Of these targets, CDCP1 is reportedly associated with PI3K/AKT signaling, CMTM6 is a critical regulator of PD-L1 in a broad range of cancer cells, while UBE2D3 is linked to NF-κB signaling and ADAM10 plays a role in TNF signaling." (PMID 38041015, 2023). "These Abs potently targeted cleaved CDCP1-expressing cancer cells as an Ab-drug conjugate, an Ab-radionuclide conjugate, and a bispecific T cell engager." (PMID 35166238, 2022). "Although CDCP1 is highly expressed on cancer cells at close to approximately 2 million copies per cell, it is also present on normal epithelial tissue." (PMID 35166238, 2022). "Confirming the precise proteolysis site(s) of CDCP1 on cancer cells is critical to designing the appropriate antigen for Ab generation." (PMID 35166238, 2022). "In summary, our work reinforces the growing literature indicating that receptor CDCP1 is a rational target for the development of receptor-targeted agents for detection and personalized treatment of a range of cancers." (PMID 36276654, 2022). "Among the 20 highest expressers of CDCP1 mRNA, 16 were from cancer tissues and four from normal head and neck region (rank #2), rectum (rank #10), skin (rank #14) and thyroid gland (rank #20)." (PMID 36276654, 2022). "Most previous studies of CDCP1 have been limited to its role in tumorigenesis and have shown that CDCP1 is critical for cancer cell survival and metastasis through intrinsic mechanisms within the tumor cells." (PMID 35951427, 2022). "Our findings from cancer xenograft models in mice and analysis of 34 normal tissues and cohorts of patient tumors, support CDCP1 as theranostic target to select cancer patients for CDCP1-directed therapies including ADCs." (PMID 36276654, 2022). "It has been reported that CDCP1 is crucial for the activation of RAS in cancer, and participates in multiple oncogenic pathways, such as EGF signaling and HGF signaling." (PMID 36090897, 2022). "CUB-domain containing protein 1 (CDCP1) is a cell surface glycoprotein that is elevated in a range of malignancies and mediates oncogenic processes promoting cancer cell survival, growth, metastasis and treatment resistance." (PMID 36276654, 2022). "This allowed mRNA analysis of normal and tumor samples from 23 malignancies and 38 normal tissues, demonstrating that CDCP1 mRNA is overexpressed in all but seven of the cancers versus the corresponding normal tissues." (PMID 36276654, 2022). "Our developed human/mouse chimeric antibody ch10D7 demonstrated efficacy at delivering payloads for detection and treatment of CDCP1 expressing cancer xenograft models in mice." (PMID 36276654, 2022). "There is a higher proportion of cleaved CDCP1 (c-CDCP1) present in more aggressive metastatic cancer cell types compared with less malignant cancer cell lines." (PMID 35166238, 2022). "Herein, we evaluated the rationale of targeting the cell surface oncoreceptor CUB domain-containing protein 1 (CDCP1) using ADCs and assessed the efficacy of CDCP1-directed ADCs against a range of malignant tumors." (PMID 36276654, 2022). "A mechanistic analysis revealed the ARHGEF7-RAC1 axis as a novel mediator of CDCP1-dependent promotion of cancer cell invasion." (PMID 35085554, 2022). "Previous studies have revealed that CDCP1 is oncogenic in several human cancers via regulating tyrosine phosphorylation-dependent cellular functions, and then promotes tumor invasion and metastasis." (PMID 36090897, 2022). "Antibody ch10D7 demonstrates a high affinity and specificity for CDCP1 inducing cell signalling via Src accompanied by rapid internalization of ch10D7/CDCP1 complexes in cancer cells." (PMID 36276654, 2022).
cancer (continued). "To evaluate expression of CDCP1 in human cancer and normal human tissues, we examined its mRNA and protein levels in cohorts of normal and malignant samples." (PMID 36276654, 2022). "Cub domain-containing protein 1 (CDCP1) is a protein that is highly expressed on the surface of many cancer cells." (PMID 35951427, 2022). "CDCP1 is overexpressed in cancer and portends a worse prognosis; previous attempts to target CDCP1 reduced cancer growth, but adversely affected the host." (PMID 35166242, 2022). "The described approaches verify the potential of targeting CDCP1 in a range of solid cancers and represent a pipeline for assessing the suitability of receptors as targets for cancer directed theranostics and ADCs." (PMID 36276654, 2022). "CDCP1 is highly overexpressed in RAS-driven cancers, and its ectodomain is cleaved by extracellular proteases." (PMID 35166238, 2022). "We were the first show colocalization of CD147 (BSG) and CD318 (CDCP1) at the surface of cancer cell line expressing KRas4B mutant." (PMID 34611477, 2021). "Mounting evidence is suggesting the pro-tumorigenic signaling protein CDCP1 as a promising therapeutic target for multiple cancer types, including at the metastatic stage." (PMID 33527138, 2021). "In some cancer cells, up-regulated CDCP1 promotes invasion, metastasis, and tumor growth, although the underlying mechanisms remain elusive." (PMID 33574034, 2021). "Of these 32, several genes (mt-Nd3, mt-Nd4l) involved in mitochondrial metabolism have emerged, as well as other genes such as Epcam and Gprc5c involved in cancer stemness and dormancy of HSCs, respectively, and Cdcp1 that is expressed on leukemic blasts." (PMID 34550965, 2021). "A proteomic search in three different cancer cell lines with a protease-reactive warhead build on CDCP1 sequences, identified uPA and plasmin as the lead candidates for cleaving CDCP1 at Arg368 or Lys369." (PMID 34490277, 2021). "Overexpression of CDCP-1 in PDAC as well as various other cancers is correlated with poor prognosis." (PMID 34885196, 2021). "Our results indicate that Alu siRNAs, very effective CDCP1 targeting small non-coding RNAs, can also be used for treatment of certain cancers." (PMID 32817447, 2020). "The structural features of CDCP1 support its potential as a target for antibody based anti-cancer agents." (PMID 32104500, 2020). "CDCP1, a transmembrane protein overexpressed in many types of cancers, suppresses apoptosis and thereby promotes their metastasis." (PMID 32817447, 2020). "These include the kinase Src which is a key regulator of CDCP1-mediated signalling in pathological settings including cancer." (PMID 32104500, 2020). "CDCP1 proteolysis can modulate its interactions with molecular partners and the metastatic potential of cancer cells 6,8,15,16." (PMID 32226543, 2020). "Its potential as a cancer target is supported by studies showing that anti-CDCP1 antibodies inhibit cell migration and survival in vitro, and tumor growth and metastasis in vivo." (PMID 32104500, 2020). "Considering its limited reported expression in normal tissues, including skin 41, colon 42 and prostate 43, these data support the potential utility of CDCP1 targeted agents to detect and treat CDCP1-expressing cancers such as EOC." (PMID 32104500, 2020). "Based on data from in vitro and animal models, CDCP1 is functionally important for each of these cancers by promoting cell survival and metastasis 11-14, as well as resistance to chemotherapy 11-15 and targeted agents 16-19." (PMID 32104500, 2020). "CDCP1 has been shown to promote survival of several different types of cancer cells by activating MYC, AKT, and Wnt gene pathways." (PMID 32817447, 2020). "CDCP1 has been proposed as a molecular target to abrogate oncogenic signalling pathways and specifically deliver anti-cancer agents to tumors." (PMID 32226543, 2020).
cancer (continued). "Recent literature shows that hypoxia-inducible factor (HIF)-2α is essential for induction of CDCP1 expression under hypoxic conditions, a common microenvironment for cancer cells that contributes to chemoresistance." (PMID 31461438, 2019). "CDCP1 interplays with the oncogenic Ras/ERK signaling to promote the cancer cell growth, migration, and invasion, and represents as a promising target for cancer therapeutics." (PMID 30796352, 2019). "The dysregulated expression of oncogene CDCP1 promotes cancer transformation and progression in vitro and in vivo." (PMID 30796352, 2019). "This study shows that CDCP1-positive cancer stem cells represent a critical driving force behind tumor relapse in colorectal tumors that have mutant Kras and reveals a unique role for the oxidative pentose phosphate pathway in this process." (PMID 31461438, 2019). "CDCP1-expressing cancer cells expressing the relevant HLA class I antigens were incubated with different concentrations of CDCP1-targeting ATPPs carrying the HLA-A01:01 binding pFLU or the HLA-A02:01 binding pEBV_1 or pEBV_2 epitopes." (PMID 31555260, 2019). "(h) Representative microPET images of four immunocompromised nu/nu mice bearing cancer xenografts targeted with a 89Zr-labeled CDCP1 Fab." (PMID 29359686, 2018). "We used CDCP1 as an example to validate that these observations extend beyond MCF10As to patient derived cancer cell lines and even to xenograft mouse models for PDAC." (PMID 29359686, 2018). "It was reported that CDCP1 is a unique HIF-2α target gene involved in the regulation of cancer metastasis and suggest that CDCP1 is a biomarker and potential therapeutic target for metastatic cancers." (PMID 28986523, 2017). "Desmoglein-2 and CUB-domain containing protein 1 (CDCP1) are biomarkers of invasive cancers and known substrates of matriptase." (PMID 28926939, 2017). "CUB-domain-containing-protein-1 (CDCP1) is an integral membrane protein whose expression is up-regulated in various cancer types." (PMID 28986523, 2017). "The growing literature demonstrating that CDCP1 expression is often elevated in cancer and that this overexpression correlates with poor outcome for various malignancies, sets the challenge for the development of effective CDCP1 targeted therapies." (PMID 26973855, 2016). "Signaling pathways regulated by the receptor CDCP1 play central roles in promoting cancer and in mediating resistance to chemo- and targeted-therapies." (PMID 26973855, 2016). "CDCP1 is an anoikis regulator, and a couple of groups have been trying to develop anti-CDCP1 Ab for cancer therapy." (PMID 27834817, 2016). "It is apparent that in these, and potentially other oncogenic settings, CDCP1 is the major substrate of Src family kinases (SFKs) and that it actively competes for Src with other mediators of pro-cancer phenotypes such as FAK." (PMID 26973855, 2016). "Signaling via CDCP1, potentially via growth factor receptor axes, can be intensified under hypoxic conditions, a common microenvironment for cancer cells that also contributes to chemoresistance." (PMID 26973855, 2016). "CDCP1-mediated pro-cancer effects can also occur via ligand/receptor-independent activation of pathways downstream of cell surface EGFR family members." (PMID 26973855, 2016). "It has also been shown that EGF activation of EGFR further accentuates CDCP1-induced pro-cancer effects by inhibiting proteasome-mediated, palmitoylation-dependent constitutive degradation of CDCP1." (PMID 26973855, 2016). "Experimental data support a role for CDCP1 in cancer progression, ECM degradation, anchorage-independent signaling, and cancer cell resistance to anoikis." (PMID 26497208, 2015). "The two membrane-bound forms of CDCP1, the HMW-CDCP1 and a shorter LMW-CDCP1 species, have been observed in various cancer cells and keratinocytes." (PMID 26497208, 2015). "CDCP1 has recently been proposed as a novel stem cell marker and as a diagnosis and prognosis marker for various cancers." (PMID 25876044, 2015).